DEPDC7 (DEP domain containing 7)
Synonyms: TR2; dJ85M6.4
Tractability: PROTAC: ubiquitination databases record sites on it.
Gene: Protein-coding gene on chromosome 11 (33,015,876 to 33,033,582, forward strand). Ensembl gene ENSG00000121690.
Subcellular location (Human Protein Atlas): Nucleoli; Cytosol; Nucleoplasm
Gene Ontology:
Biological process: intracellular signal transduction
Genetic constraint (gnomAD): Loss-of-function variants: 34 observed, 45.91 expected, observed/expected ratio (o/e) 0.74, 90% interval 0.56 to 0.99. The upper end of that interval is the gene's LOEUF score, 0.99, which puts it in group 4 of 6, group 1 being the genes least tolerant of losing a copy. Missense variants: 481 observed, 557.79 expected, observed/expected ratio (o/e) 0.86, 90% interval 0.8 to 0.93. Synonymous variants: 181 observed, 198.26 expected, observed/expected ratio (o/e) 0.91, 90% interval 0.81 to 1.03.
Homologues: Orthologues: chimpanzee DEPDC7 (99% identical), macaque DEPDC7 (94% identical), dog DEPDC7 (92% identical), pig DEPDC7 (90% identical), guinea pig DEPDC7 (88% identical), mouse Depdc7 (87% identical), rat Depdc7 (84% identical), tropical clawed frog depdc7 (63% identical), zebrafish depdc7a (50% identical), zebrafish depdc7b (45% identical), Caenorhabditis elegans let-99 (16% identical). Paralogues in human: DEPDC4 (34% identical), DEPDC1B (23% identical), DEPDC1 (22% identical).
Diseases named in the same sentence as DEPDC7 in open-access papers:
DEPDC7 is named in the same sentence as 9 diseases in open-access papers, as found by Europe PMC text mining. Sharing a sentence is not in itself a finding about the gene and the disease. The quoted sentences say what the papers report.
hepatocellular carcinoma (2 papers, 2020 to 2026). A malignant tumor that arises from hepatocytes. "The knockout of DEPDC7 promotes cell growth, migration, and invasion in hepatocellular carcinoma, which indicates that it is related to the proliferation and migration of liver cancer cells." (PMID 32528134, 2020).
breast tumor (1 paper, 2023). "RNA-sequencing of wild-type versus HIF-2α-deficient TAMs in murine breast tumors demonstrated 3 more genes Spint1, IL-10, and Depdc7 were downregulated by HIF-2α knockout and had an identified HIF-2α (not HIF-1α) binding site using previously published ChIP-seq data sets." (PMID 37124241, 2023).
depression (1 paper, 2023). "However, it has been suggested that DEPDC7 DNA hypomethylation may be associated with depression." (PMID 37672513, 2023).
lung carcinoma (1 paper, 2020). "In addition, RUFY1, DEPDC7, and IRF4 were reported to be involved in lung cancer." (PMID 33051402, 2020).
tumor (2 papers, 2023 to 2026). "Perhaps, HIF-2α-induced Depdc7 in TAMs limits migration and invasion in tumors and promotes NF-κB-mediated pro-inflammatory transcription to stimulate immune responses to control tumor progression." (PMID 37124241, 2023).
infection (1 paper, 2025). The state of being infected such as from the introduction of a foreign agent such as serum, vaccine, antigenic substance or organism. "The downregulated lncRNA A230001M10Rik is strongly correlated with Fabp7, Slc2a5, and Depdc7, which might suggest potential roles in neural homeostasis, glial metabolism, and cellular proliferation during infection." (PMID 41214723, 2025).
DEPDC7 also shares sentences with these, for which no sentence is quoted: Azoospermia (1 paper); cryptorchidism (1); liver cancer (1).